SESN2 (sestrin 2)
Diseases named in the same sentence as SESN2 in open-access papers (continued):
Sharing a sentence is not in itself a finding about the gene and the disease.
pneumonia (1 paper, 2025). An acute, acute and chronic, or chronic inflammation focally or diffusely affecting the lung parenchyma, caused by an infection in one or both of the lungs (by bacteria, viruses, fungi, or mycoplasma.). "In this study, we aimed to investigate the association between SESN2 and pneumonia, with the potential of utilizing SESN2 as a clinical biomarker and prognostic indicator in pediatric pneumonia." (PMID 41303741, 2025). "Addressing oxidative stress, inhibiting excessive ROS production, and increasing SESN2 levels could be important strategies for reducing pneumonia-associated complications." (PMID 41303741, 2025). "The use of SESN2 as a clinical biomarker and prognostic factor in pediatric pneumonia can provide significant advances in pediatric healthcare." (PMID 41303741, 2025). "For this purpose, SESN2 can be used as a clinical biomarker and prognostic factor in pediatric pneumonia." (PMID 41303741, 2025). "In other words, as pneumonia severity increases, the body’s protective SESN2 response diminishes, leading to a less effective defense against the harmful effects of inflammation and oxidative stress." (PMID 41303741, 2025). "Mitigating oxidative stress, blocking the elevated ROS levels, and increasing SESN2 levels may be an important step in reducing pneumonia-related complications." (PMID 41303741, 2025).
renal cell carcinoma (1 paper, 2023). "These 27 CTTs including 8 genes CTNNA1, PSMB6, PSMD12, SESN2, SLC22A2, UBE2J2, and NAE1 appeared in the SL pairs of renal cell carcinoma in previous literature studies." (PMID 38074121, 2023).
renal fibrosis (1 paper, 2025). A final common manifestation of a wide variety of chronic kidney diseases characterized by glomerulosclerosis and tubulointerstitial fibrosis. "The UACR decreased in the SESN2-exo injection group, while renal fibrosis, impaired autophagic degradation and Kim-1 expression were alleviated in the mice injected with SESN2-exos." (PMID 40612680, 2025). "As expected, AAV-sh-SESN2 aggravated db/db mouse UACR, renal fibrosis and Kim-1 expression." (PMID 40612680, 2025).
sarcopenia (1 paper, 2020). Progressive decline in muscle mass due to aging which results in decreased functional capacity of muscles. "We previously found that Sesn2 expression in the heart gradually decreased with age, which suggests that Sesn2 is an age-related protein, recently showed that sestrins protect against aging-related sarcopenia in mice." (PMID 32863202, 2020).
skin cancer (1 paper, 2016). "SESTRIN 2 induction has been reported in other cancer models including skin cancer where it was also linked cell survival." (PMID 26930721, 2016).
triple-negative breast carcinoma (1 paper, 2016). An invasive breast carcinoma which is negative for expression of estrogen receptor (ER), progesterone receptor (PR), and human epidermal growth factor receptor 2 (HER2).
uveitis (1 paper, 2025). An inflammatory process affecting a part of or the entire uvea. "This study aims to investigate SESN2's regulatory effects on ferroptosis in LPS‐induced inflammation and elucidate the underlying signaling pathways in uveitis." (PMID 41294929, 2025). "SESN2 plays a crucial role in protecting against inflammation and ferroptosis via the Nrf2 pathway, presenting a promising therapeutic target for uveitis management." (PMID 41294929, 2025). "This study investigates SESN2's role in modulating inflammation and ferroptosis in endotoxin‐induced uveitis (EIU) models, aiming to develop safer therapeutic alternatives for uveitis management." (PMID 41294929, 2025). "While SESN2 is critical in maintaining cellular homeostasis under stress conditions, its potential involvement in iron overload‐induced uveitis remains unexplored." (PMID 41294929, 2025).
cancer (64 papers, 2010 to 2025). A tumor composed of atypical neoplastic, often pleomorphic cells that invade other tissues. "Altogether, SESN proteins and SESN2 in particular are implicated in tumour onset and progression of the several types of human cancer." (PMID 37284849, 2023). "Despite the fact that SESN2 generally antagonizes colon tumor growth, it can promote tumorigenesis in an iron-rich environment by suppressing cancer cell death associated with oxidative stress." (PMID 36980973, 2023). "Recent studies linking SESN2 with the occurrence and development of cancer have highlighted its potential as a diagnostic and therapeutic target." (PMID 37059726, 2023). "In other cancers such as prostate and bladder cancer, increased SESN2 expression is also associated with attenuated proliferation, increased apoptosis and autophagy as well as anchorage-independent growth." (PMID 36611970, 2022). "SESN2 silencing was associated with a nearly threefold increase in ROS and shortened cancer cells survival." (PMID 35527284, 2022). "SESN2/Sestrin 2 is a stress-inducible protein that is induced under hypoxic conditions and is reported to be associated with oxidative-stress-induced autophagy; indeed, the occurrence of cancers is associated with significant downregulation of SESN2." (PMID 35743294, 2022). "Although sestrin 2 is associated with colorectal, lung, liver, and other cancers, sestrin 2 expression varies among different types of cancer, and the effects and mechanisms of action of this protein are also different." (PMID 34784907, 2021). "While accumulating evidence suggests an association between Sesn2 and aging, new reports have demonstrated that Sesn2 plays a role in cancer, inflammation, and neurological diseases." (PMID 32010489, 2020). "Taken together, our findings suggest that the anti-cancer effect of fisetin on HNCCs is associated with SESN2/mTOR/Mcl-1 signaling axis." (PMID 30936621, 2019). "Recent studies have indicated that a low level of SESN2 is associated with progression and poor prognosis in different types of cancer patients or tumor models." (PMID 31867002, 2019). "Loss of heterozygocity (LOH) in Sesn1 (6q21) and Sesn2 (1p35) is also often observed in diverse human cancers." (PMID 25962159, 2015). "Inaddition, Sestrins can suppress the growth of some cancer cell lines andloss of Sesn2 makes immortalized cells more susceptible to oncogenictransformation." (PMID 20606249, 2010). "Sestrin2 (Sesn2), a stress-inducible protein, has been implicated in various cancers, but its precise role and mechanism in OSCC remain unclear." (PMID 41614860, 2025). "Therefore, the deficiency of SESN1 or SESN2 supports the growth of tumor xenografts and potentially contributes to cancer progression, but their role in carcinogenesis is poorly understood." (PMID 39985075, 2025). "In addition, we found that EXOSC4 knockdown caused the upregulation in mRNAs’ levels of BIK and SESN2, both of which induce apoptosis in cancer cells." (PMID 35008922, 2022). "However, the function of sestrin 2 in regulating cancer is bidirectional, and the underlying mechanisms need further exploration and verification." (PMID 34784907, 2021). "In addition to regulating mTOR and iNOS pathways, sestrin 2 has been shown to promote cancer cell apoptosis by targeting X-linked inhibitor of apoptosis protein (XIAP) and suppress cell migration and invasion by targeting hypoxia inducible factor-1α (HIF-1α)." (PMID 34784907, 2021). "As a novel diagnostic and therapeutic target, the paradoxical role of sestrin 2 in cancers may hinder clinical application in the future." (PMID 34784907, 2021). "The anti-cancer effects of SESN2 are associated with regulation of the mTORC1 signaling pathway." (PMID 32899752, 2020).
cancer (continued). "Additionally, low levels of SESN2 are associated with poor prognosis in patients with different cancer types." (PMID 32899752, 2020). "Given that SESN2 is greatly implicated in protecting cancer cells from apoptosis and promoting cell survival via AKT and AMPK, we hypothesized that it might confer primary resistance to sorafenib by activating AKT and AMPK in HCC." (PMID 30311444, 2018). "Thus far, studies concerning the association between SESN2 and cancer mortality in clinical samples are rare." (PMID 28118855, 2017). "The SESN1 (6q21) and SESN2 (1p35) loci are frequentlydeleted in a variety of human cancers, implicating loss of Sestrinsin tumor progression and suggesting that Sestrin-dependent inhibition of TORC1is critical for suppressing tumorigenesis spurred by age-dependent accumulationof damaged DNA." (PMID 20606249, 2010). "Therefore, restoration of Sestrin activity or STAT3 inhibition in SESN1&2-deficient cancer cells may be a potential strategy to improve the treatment outcome for patients with cancers bearing mutations in SESN1 or SESN2 genes." (PMID 39985075, 2025). "Notwithstanding the need to explore in more detail as to which cancers and genetic subtypes gain advantage from this mechanism, it will be interesting to explore whether other mRNAs associated with different metabolic pathways are also targeted by SESN2." (PMID 37059726, 2023). "Besides, studies have demonstrated that sestrin 2 is associated with immune system diseases, liver diseases, ischemic-reperfusion lesions, neurodegenerative diseases, cardiovascular disorders, aging, and cancer." (PMID 34784907, 2021). "According to the studies mentioned, SESN2 functions as a tumor suppressor gene in specific cancers, possibly through the AMPK/mTOR signaling pathway." (PMID 40775338, 2025). "Recent studies have demonstrated that SESN2 plays a role in the development and progression of various human cancers." (PMID 40661871, 2025). "Our preliminary findings suggest that SESN2 exerts anti-cancer effects in PCa, possibly by inhibiting AMPK phosphorylation, leading to the activation of the mTOR signaling pathway." (PMID 40775338, 2025). "The function of Sesn2 exhibits pronounced heterogeneity across different cancer types, and this dual role constitutes a central challenge in its translational investigation." (PMID 41614860, 2025). "Sesn2 acts as a cancer biomarker and potential therapeutic target, playing a critical role in cancer occurrence and progression." (PMID 41614860, 2025). "The authors showed that intracellular ROS was significantly increased in suspended cells with silenced SESN2, and ROS correlated with the number of metastases induced via intravenous injection of cancer cells." (PMID 40361504, 2025). "Other studies also suggest that sestrin-2-mediated autophagy has antiproliferative effects in some cancer cells." (PMID 38396629, 2024). "It should be noted that sestrin-2 expression varies among different types of cancer and both a tumor suppressor and a tumor promoter role has been indicated in different studies." (PMID 38732504, 2024). "Several studies have confirmed that SESN2 can promote apoptosis of multiple types of cancer cells, including human head and neck cancer cells, lung adenocarcinoma cells, and colon cancer cells." (PMID 36841824, 2023). "The considerable importance of this work lies in the combination of cancer cells’ nutrient stress and the prevention of excessive accumulation of ROS with SESN2, mTORC1 and mTORC2." (PMID 37284849, 2023). "They proved that SESN2 attenuates cancer cell growth primarily through inhibition of a hyperactive mTORC1." (PMID 37284849, 2023).
cancer (continued). "In another study, Zhang and colleagues revealed that C-Jun NH2-terminal kinase (JNK), which is commonly activated in cancer, is involved in the regulation of SESN2 transcription during autophagy." (PMID 37284849, 2023). "Certainly, the shutdown of proliferation by SESN2 is beneficial for preserving cancer cell vitality but this must be reversed when glucose levels are sufficient to support proliferation." (PMID 37059726, 2023). "In several human cancer cell lines, chronic activation of the mTORC1 complex leads to increased SESN2 expression." (PMID 37284849, 2023). "Collectively, our findings reveal an intrinsic survival mechanism allowing cancer cells to overcome chronic glucose shortages, also providing new mechanistic insights into SESN2 as an RNA-binding protein with a role in reprogramming of cancer cell metabolism." (PMID 37059726, 2023). "The study showed that SESN2 knockdown in a non-small cell lung cancer can decrease cancer cells stemness, proliferation, and migration and improve their chemoresistance." (PMID 35527284, 2022). "In these cancers, sestrin 2 was verified as an oncogene, which suppressed apoptosis and promoted drug and anoikis resistance." (PMID 34784907, 2021). "Recent studies have shown that sestrin 2 is a cancer biomarker and potential therapeutic target that is critical for cancer occurrence and development." (PMID 34784907, 2021). "In contrast, SESN2 expression is reported to be largely suppressed in many cancers, despite the high level of reactive oxygen species, but there are also reports of increased SESN2 expression in some cancers." (PMID 34611283, 2021). "Kumar et al70 demonstrated that SESN2 facilitated cancer cell survival under glucose starvation conditions by modulating glutamine metabolism." (PMID 33942488, 2021). "Together, these studies revealed that sestrin 2 is a vital regulator of cancer cell survival under the conditions of glycolysis inhibition, glutamine deficiency, glucose starvation, high iron, and ER stress." (PMID 34784907, 2021). "Bruening et al37 found that the upregulation of SESN2 was associated with the expression of ER stress markers ATF4, ATF3 and C/EBP‐homologous protein (CHOP) in cancer cells." (PMID 33942488, 2021). "In this review, we will examine the state of research on sestrin 2 in different types of cancers and demonstrate its role in inhibition and promotion of cancer by focusing on related mechanisms." (PMID 34784907, 2021). "This study demonstrated the crucial role of sestrin 2 in regulating cancer cell survival under glucose starvation conditions." (PMID 34784907, 2021). "Activation of multiple stresses, including ER stress and oxidative stress, by dysregulated activation of mTORC1, initiates a negative-feedback loop to suppress mTORC1 activity by transcriptional activation of SESN2 during cancer cell growth and expansion." (PMID 32899752, 2020). "Although SESN2 is widely known as a potential therapeutic target for various types of cancer, to the best of our knowledge, this is first report to demonstrate the involvement of SESN2 signaling in the antitumor activity by adiponectin." (PMID 32155890, 2020). "To further clarify the upstream signaling mechanisms by which gAcrp suppresses inflammasomes activation in cancer cells, we examined the role of SESN2 signaling." (PMID 32155890, 2020). "In many cancer cells, overexpression of SESN2 contributes to inhibition of cell growth through AMPK phosphorylation, the mammalian target of rapamycin (mTOR) inhibition, and autophagy induction." (PMID 32155890, 2020). "Next, we investigated the correlation between SESN2 and cell cycle-associated genes, including CDKN1A (encoding p21) and CDKN1B (encoding p27), by analyzing RNA expression data for cancer patients using the GEPIA database." (PMID 32899752, 2020). "The analysis indicated increased levels of SESN2 and mTORC1 pathway activity in cancer tissues than in normal tissues." (PMID 32899752, 2020).
cancer (continued). "Previous studies have demonstrated that Sesn2 suppresses the proliferation of human carcinoma cells, fibroblasts, and epithelial cells." (PMID 32528056, 2020). "SESN2 expression is reportedly reduced in cancer tissues compared to normal tissues, and it is lost or downregulated during the carcinogenesis of CRC." (PMID 31337142, 2019). "SESN2, sestrin 2 was enriched in this pathway which was reported to involve with various cancers such as bladder, breast, and lung cancers." (PMID 29991755, 2018). "The survival results were also in line with those of earlier studies, where high SESN2 expression prohibits tumor development and predicts favorable prognosis in cancers." (PMID 28118855, 2017). "Previous studies have indicated that sestrin 2 expression in cancer cells suppresses cell growth and proliferation by leading to the negative control of mTOR through AMPKα1 phosphorylation." (PMID 24535669, 2014). "With high oral bioavailability and tolerable side effects, metformin remains an attractive candidate, although its efficacy as an anti-cancer adjuvant remains inconclusive, and its utility for SESN2 activation in oncological contexts requires further investigation." (PMID 40361504, 2025). "In short, Sesn2 function differs in different types of cancer." (PMID 41614860, 2025). "As SESN2 is an important component in cancer, it may be worth further investigation for the treatment of prostate disease." (PMID 40661871, 2025). "Sestrin2 (SESN2) has antitumor activity against several types of cancers." (PMID 40661871, 2025). "SESN2 may serve as potential therapeutic targets for metabolic disorders, cardiovascular and neurodegenerative diseases, and cancer." (PMID 40661871, 2025). "The function of SESN2 in different cancer cells may depend on the species or cellular metabolic conditions." (PMID 36841824, 2023). "In conclusion, these experiments suggest that SESN2 may serve as a pro-cancerous protein increasing cancer cells chemoresistance in specific circumstances such as endoplasmic stress." (PMID 37284849, 2023). "Previous studies indicated that SESN2 could alleviate oxidative stress via nuclear factor erythroid 2-related factor 2 (Nrf2), and thus favor cancer cell survival." (PMID 36980973, 2023). "All of this suggests that the restoration of SESN2 expression could be beneficial for improving the therapeutic response to anti-cancer drugs." (PMID 37284849, 2023). "Indeed, SESN2 has been shown to make important contributions to different cancer-related functions including but not limited to roles in regulating cell proliferation, invasion, apoptosis, autophagy, metastasis, and drug resistance." (PMID 37059726, 2023). "Likewise, contradictory results have been described for sestrin-2 and tumor pathology, since bidirectional functions (as tumor-suppressing and oncogene) have been found for this protein in various cancer types." (PMID 35162104, 2022). "Immune assays and online measurements of cellular bioenergetics were employed to investigate the nature of Sestrin2 regulation, and finally, by silencing the SESN2 gene, to identify the role of induced Sestrin2 upon a single amino acid deprivation in cancer cells of various origins." (PMID 36497120, 2022). "SESN2 is reported to activate autophagy via the AMPK/mTOR pathway in cancers." (PMID 36588732, 2022). "Sestrin 2 facilitates metastasis and cancer anoikis resistance." (PMID 34784907, 2021).